PLEKHG6 (pleckstrin homology and RhoGEF domain containing G6)
Description:
Guanine nucleotide exchange factor activating the small GTPase RHOA, which, in turn, induces myosin filament formation. Also activates RHOG. Does not activate RAC1, or to a much lower extent than RHOA and RHOG. Part of a functional unit, involving PLEKHG6, MYH10 and RHOA, at the cleavage furrow to advance furrow ingression during cytokinesis. In epithelial cells, required for the formation of microvilli and membrane ruffles on the apical pole. Along with EZR, required for normal macropinocytosis.
Synonyms: MyoGEF; FLJ10665; ARHGEF46
Tractability: No criterion of Open Targets' tractability assessment is met for any kind of drug.
Gene: Protein-coding gene on chromosome 12 (6,310,225 to 6,328,934, forward strand). Ensembl gene ENSG00000008323.
Subcellular location: Cell projection, microvillus; Cytoplasm, cytoskeleton, spindle; Cytoplasm, cytoskeleton, spindle pole; Cleavage furrow
Subcellular location (Human Protein Atlas): Cell Junctions; Centrosome
Pathways (Reactome):
Signal Transduction: RAC1 GTPase cycle; RHOA GTPase cycle
Gene Ontology:
Molecular function: protein binding; guanyl-nucleotide exchange factor activity; GTPase activator activity
Biological process: regulation of small GTPase mediated signal transduction
Cellular component: cell junction; cleavage furrow; cytosol; cytoplasm; microvillus; spindle; spindle pole
Genetic constraint (gnomAD): Loss-of-function variants: 83 observed, 84.54 expected, observed/expected ratio (o/e) 0.98, 90% interval 0.82 to 1.18. The upper end of that interval is the gene's LOEUF score, 1.18, which puts it in group 5 of 6, group 1 being the genes least tolerant of losing a copy. Missense variants: 1,033 observed, 963.65 expected, observed/expected ratio (o/e) 1.07, 90% interval 1.02 to 1.13. Synonymous variants: 465 observed, 396.38 expected, observed/expected ratio (o/e) 1.17, 90% interval 1.09 to 1.27.
Homologues: Orthologues: chimpanzee PLEKHG6 (99% identical), macaque PLEKHG6 (95% identical), pig PLEKHG6 (84% identical), dog PLEKHG6 (82% identical), mouse Plekhg6 (82% identical), rabbit PLEKHG6 (81% identical), rat Plekhg6 (80% identical), guinea pig PLEKHG6 (76% identical), zebrafish plekhg6 (28% identical), Drosophila melanogaster RhoGEF2 (17% identical), Drosophila melanogaster cyst (15% identical), Caenorhabditis elegans prhg-1 (15% identical), and 1 more. Paralogues in human: ARHGEF2 (17% identical), ARHGEF18 (17% identical), ARHGEF11 (17% identical), ARHGEF12 (16% identical), ARHGEF28 (16% identical), ARHGEF1 (14% identical), NET1 (11% identical), ARHGEF3 (9% identical).
Diseases named in the same sentence as PLEKHG6 in open-access papers:
PLEKHG6 is named in the same sentence as 8 diseases in open-access papers, as found by Europe PMC text mining. Sharing a sentence is not in itself a finding about the gene and the disease. The quoted sentences say what the papers report.
bladder cancer (1 paper, 2017). "Further analysis of the 3 independent bladder cancer datasets have identified ACOX1, UPK2, TRAK1, PLEKHG6 and MT1X genes had their expression significantly correlated with that of DAPK1." (PMID 28388658, 2017).
cancer (1 paper, 2022). A tumor composed of atypical neoplastic, often pleomorphic cells that invade other tissues. "In CRC, the SNP rs11064124G > A in a cancer-specific SE at 12p13.31 promotes its binding affinity to vitamin D receptor (VDR), resulting in the greatly reduced expression of the tumor suppressor genes CD9 and PLEKHG6, which leads to cancer cell proliferation." (PMID 35277481, 2022).
PLEKHG6 also shares sentences with these, for which no sentence is quoted: breast carcinoma (1 paper); colon tumor (1); colorectal cancer (1); glioma (1); melanoma (1); tumor (1).